IL4 (interleukin 4)
Diseases named in the same sentence as IL4 in open-access papers (continued):
Sharing a sentence is not in itself a finding about the gene and the disease.
infection (continued). "At all time points after infection, the percentages and absolute numbers of IFN-γ-producing and IL-4-producing cells in the spleens and livers of infected highly resistant p110δD910A mice were significantly lower than those from their infected WT counterpart mice." (PMID 24945303, 2014). "For infections with L. naiffi, higher levels of TNF-α and IL-4 were consistently detected in comparison to infections with L. guyanensis and L. amazonensis, though no statistical differences were observed." (PMID 25295285, 2014). "Neither IL-4 nor IL-5 was detected and high levels of IL-10 (1661±341 pg/ml) were maintained after infection." (PMID 25144756, 2014). "In a murine model, infection with H. polygyrus and S. mansoni eggs (a complete infectious cycle was not tested) could reactivate the mouse γ-herpes virus MHV68 in vivo, via an IL-4- and Stat6-dependent pathway." (PMID 25398130, 2014). "In the very first week after infection the vaccinated mice produced less than half the amount of IL-10 and IL-4 compared to the non-vaccinated mice." (PMID 23825956, 2013). "In this study, expression levels of IL-4, IL-10, IL-13 and TNF-α were significantly up-regulated while the expression levels of IL-1β,IL-18,IFN-γ, IL-2, IL-15, IL-17F, IFN-α, IFN-β, IL-3 and CSF-1 were markedly decreased in PBMCs at all stages of infection." (PMID 24358317, 2013). "Conversely, “non-healer” BALB/c mice are unable to control infection and develop a Th2 immune response characterized by the production of IL-4 and IL-13 cytokines." (PMID 24204259, 2013). "As observed before challenge, the ratio between IFN-γ/IL-4 and IFN-γ/IL-10, and between IL-12/IL-4 and IL-12/IL-10 indicated that vaccinated mice developed a specific Th1 immune response, which was maintained after infection in these animals (respectively)." (PMID 23573301, 2013). "For the lung-LN response, only the IFN-γ levels showed a significant increase at the latest time point of infection compared to the NI level (p = 0.036); there was no change in IL-4 or IL-10 over the infection period." (PMID 24086786, 2013). "In the spleens, similar to the JaOArS982 infection, the levels of IFN-γ, IL-2 and IL-4 in IL-10 KO and TNF-α KO mice were significantly increased compared with those of WT mice at 7 days pi following JaTH160 infection, whereas the level of IL-5 was decreased in TNF-α KO." (PMID 23940775, 2013). "Further, we did not detect the presence of IL-4, IL-5 or IL-13 in culture supernatants at any time after infection among cells infected with MOI = 50 with LVS or SchuS4." (PMID 24324751, 2013). "In addition, except for 4 of the regulatory genes (IRF4, JAK1, NFATC4 and STAT6), many of the other genes in this pathway were only transiently expressed at 2 (IL4R and PTPRC) or 4 and/or 8 (IL13, IL4 and CEBPB) weeks post-infection." (PMID 23448601, 2013). "At 1 dpi, a statistical difference in the upregulation of interleukin-4 (IL-4), interleukin-6 (IL-6), tumor necrosis factor (TNF), and interferon-γ (IFNγ) was observed between NiV-M and NiV-B infections, with higher expression of these genes in response to NiV-M." (PMID 23342177, 2013). "In contrast, Group 3 neonates with active infections and no AAD, produced significantly elevated levels of IFN-g, IL-5, and IL-4 when compared to group 3 adults which had cleared infections and had no AAD (P = 0.0092, 0.0152, and 0.0362 respectively)." (PMID 24376704, 2013). "In the cases of Th2 cytokines, IL-4 levels were low on days 1 and 5 after infection and the effects of AF-08 and/or TBBPA were not obvious." (PMID 24250719, 2013). "Hepatic CD8+ T cells produced neither IL-4 nor IL-13 throughout the infection although obvious IFN-γ production was observed (data not shown)." (PMID 24358216, 2013).
infection (continued). "Several cytokines, such as the granulocyte macrophage colony-stimulating factor (GM-CSF), IL-1α, TNF-α, IL-10, IL-17A, IL-2, IL-4 and IL-5, showed a slight but non-significant increase in their serum concentrations upon infection (data not shown)." (PMID 23776551, 2013). "There was a slight non-significant drop in skin IFN-γ following infection, and IL-4 levels remained fairly constant in each group." (PMID 24086786, 2013). "CD4+ T cells do not commit to the Tfh lineage until days 6–10 of infection 39, and at day 7 of H. polygyrus infection, on the cusp of Tfh-cell commitment, the numbers of IL-4 and IL-13 producing CD4+ T cells in the MLNs were equivalent in WT and ICOS−/− mice." (PMID 23319295, 2013). "However, MDM treated in vitro with IL-13 or IL-4 express DC-SIGN and, hence, can mediate HIV-1 trans infection." (PMID 24278768, 2013). "As both control mice and Itgb8 (CD11c-Cre) mice did not display production of IL-4 early during T. muris infection, these mice allowed us to test the role of the enhanced IL-13 response seen early during infection in Itgb8 (CD11c-Cre) mice." (PMID 24098124, 2013). "Interestingly, there were also significant increases in the concentrations of the Th2-type cytokines IL-4 and IL-5 in DR1 mice after PR8 infection." (PMID 22457834, 2012). "While no endogenous production of IL-4 is detected at any time during infection, there is a predominance of IgG3 and IgG2a, with a minimum response of IgG1 at the end of the acute phase and up to the 14th week pi." (PMID 22500859, 2012). "The functional heterogeneity of AM is driven primarily by pathogens and environmental IFNγ and IL-4 ratios; disruption of influences that control the CAM and AAM balance could have severe consequences on airway inflammation and resolution of infection." (PMID 22792355, 2012). "Anti-Brucella antibodies and IL-4 are not detected in serum or in spleen cells at the onset of the infection." (PMID 22500859, 2012). "However, we observed particularly for day 1 after infection, the extent of NS1 and 4G2 percentage positive cells was significantly greater for IL-4 treated CD16+ monocytes as compared to CD16- monocytes." (PMID 22574162, 2012). "As seen during the natural infection, Shigella infection of rabbit ileal loops led to a large increase in mRNA abundance for the pro-inflammatory cytokines IL-1β, TNF- α, IL-6, IL-4, IFN-γ and IL-8, highlighting the similar cytokine response elicited in the two systems." (PMID 22675469, 2012). "It has been reported that in cattle experimentally infected with M. bovis the expression of IFN-γ, TNF-α, iNOS and IL-4 by PBMCs increase in response to infection, andthat animals with high pathology express more IFN-γ, TNF-α, iNOS and IL-4 than animals with low pathology." (PMID 23251517, 2012). "This may reflect an increase in the ratio of IFN-γ-secreting to IL-4-secreting CD4 T cells, as we demonstrated in DR1 mice after infection with PR8 compared with NC." (PMID 22457834, 2012). "The expression of the Th2 cytokine IL-4, the Th17 cytokine IL-17, as well as of IL-10, was low and did not vary during infection regardless immunization." (PMID 22413022, 2012). "Based on our findings that the ratio of IL-4 to IFNγ was greater in neonatal compared to adult animals following RSV infection, we sought to compare age-dependent AM phenotypes following RSV- or mock-infection." (PMID 22792355, 2012). "Only one severely diseased non-depleted animal showed a high serum concentration of IL-4 post infection." (PMID 22533922, 2012). "We previously showed that infection with T. gondii before OVA sensitization resulted in a decrease in Ag-specific IL-4 and IL-5 production by thoracic lymph node cells with no significant increase in IFN-γ secretion." (PMID 22952678, 2012).
infection (continued). "Using this information in the current study, we demonstrate that the pattern of secretion of IL-2, IFN-γ, and IL-4 by CD4 T cells activated by NC infection is largely independent of epitope specificity and the magnitude of the epitope-specific response." (PMID 22457834, 2012). "IL-4 and IFN-γ were measured in the sera on Days 8 and 12 after infection with the PR8 virus." (PMID 23223215, 2012). "IPSE has been shown to induce basophil release of IL-4 in vivo, providing an early innate source of this polarizing TH2 cytokine at the infection site, and possibly within the draining mesenteric lymph nodes, as basophils can migrate to secondary lymphoid tissue upon activation." (PMID 22360486, 2012). "In L. major infection, different grades of resistance to infection could be seen in mice that produce similar levels of IFN-γ but varying levels of IL-4, suggesting that the magnitude of the IL-4 response determines the severity of disease more than IFN-γ." (PMID 21390155, 2011). "IL-4 was found to increase in all other control groups post challenge with M. tb presumably because of the spread of infection (data not shown)." (PMID 21853054, 2011). "Together, our results suggest that initial development of the L. mexicana lesion is dependent on an IL-4/13-responsive non-T cell population, whilst progressive infection is dependent on CD4+ T cells responsive to IL-4." (PMID 21245915, 2011). "At 3 months post-infection, both STP and LTP studies revealed that mice vaccinated with HPB vaccination could significantly down regulate IL-4 in comparison to controls (p<0.01)." (PMID 21311597, 2011). "In contrast, demyelination was not detectable after infection of the mice with wild-type (wt) HSV-1 alone or infection of the mice with the HSV-IL-4 or HSV-IFN-γ viruses, which are identical to HSV-IL-2 except that they express IL-4 or IFN-γ instead of IL-2." (PMID 21364747, 2011). "Although il12p40, il4, and il10 levels after immunization were increased compared with post-infection, the differences were not significant." (PMID 20976218, 2010). "IL-4 production was weakly induced by anti-CD3 challenge, but not using Leishmania lysate, with L. major[pcosP46] infection causing a slightly stronger response." (PMID 20345655, 2010). "Exposure of mice and humans to cercariae of the avian schistosome Trichobilharzia regenti, which does not result in patent infection, also results in induction of IgE responses and sensitization of basophils to produce IL-4." (PMID 21078176, 2010). "With progressive infection, levels of IFN-γ and IL-12 remained low although pronounced stimulation of IL-4 and IL-10 (p<0.001) compared to the level before infection, were observed in the supernatants from splenocytes of control infected mice stimulated with different antigens." (PMID 19503834, 2009). "In C. parvum infection, IL-4 may regulate the secretion of IFN-γ, and hence sustain intestinal homeostasis by limiting the recruitment of inflammatory cells in response to infection." (PMID 19247447, 2009). "For example, although Leishmania major evokes an IL-4 response in IL-12p40 KO mice, the diminished Th1 response observed in STAT4-deficient mice following infection with L. major or Toxoplasma gondii was not accompanied by a compensatory Th2 response." (PMID 18990205, 2008). "The decrease of CD4+CD25+ cells before infection did not result in the increased production of IL-4 and other cytokines in C57BL/6 mice." (PMID 18414636, 2008). "Among them, IFN-α (1000 pg/ml at 16 h), IL1RA (750 pg/m), IL4 (13 pg/m) and the proinflammatory cytokines IL-6 (1250 pg/m) and TNF-α (1700 pg/m) were induced much more rapidly after MV-EDIII-ectoM infection and at levels 8–10 times higher than after MV-EDIII infection." (PMID 18160988, 2007).
infection (continued). "The lack of protection against a challenge infection in SGS immunized mice can therefore be correlated with the low IFN-γ to IL-4 ratio observed throughout the infection period, an effect not observed in PBS inoculated mice." (PMID 18060088, 2007). "Transcripts for several other cytokines (IL-2, IL-4, IL-10, and IL-12) were detected on the array, but their levels did not change significantly during the course of infection." (PMID 17725815, 2007). "In viewof the importance of IL-13, or of the shared receptor between IL-4and IL-13, our data do not allow us to exclude the possibilitythat IL-4 synergizes with IL-13 to downregulate CXCL-8 productionduring infection with M. bovis BCG." (PMID 16864907, 2006). "In addition, we observed that infection induced the upregulation of IL2 and IL4 in M." (PMID 41675929, 2026). "LAG3 deficiency further enhanced the production of interferon-y (IFN-γ), IL-4, and IL-10 by splenic CD4+ T cells in the initial infection phase, which may contribute to the slight suppression of E. multilocularis growth and development observed in the livers of LAG3-knockout mice." (PMID 41680821, 2026). "Although we could not reliably measure IL‐4, we found IL‐13 in the cavity fluid to be strongly induced by infection and not to be affected by CD154 blocking." (PMID 41388224, 2025). "Systemic S- and N-specific IFN-γ, and IL-4 producing T cell responses measured before infection did generally not correlate with virus loads post infection, except for S-specific IFN-γ responses measured at week 18, that showed negative correlation with virus replication in throat and lung." (PMID 41390777, 2025). "Therefore, to explore the source of IL-4 in LincR-PPP2R5C KO-infected mice, flow cytometry was used to detect the expression level of IL-4 in T cells and non-T cells in the lung tissues of WT and LincR-PPP2R5C KO mice at 21 days post infection." (PMID 39287443, 2024). "The negative control group without infection expressed basal levels of IL-4." (PMID 39185043, 2024). "In addition, some studies found that the levels of IL‐2, IL‐4, IL‐6, IL‐7, IL‐10, IP‐10, MCP‐1, TNF‐α, MIP‐1α, IFN‐γ, and G‐CSF in patients with severe COVID‐19 infection were significantly higher than those in patients with mild and moderate infection." (PMID 36684101, 2023). "As the Salmonella cell wall contains trehalose phospholipids that bind to and activate MINCLE, it is possible that induction of IL-17-producing cells during infection requires MINCLE and may be inhibited by schistosome eggs through IL-4/IL-13-induced downregulation of the receptor." (PMID 36753434, 2023). "Notably, infection of neonatal mice with RSV enhanced the airway hyperreactivity response to subsequent allergen challenge, with higher eosinophil, macrophage and CD4+ T cell accumulation and elevated IL-4, IL-5 and IL-13 cytokines." (PMID 37795093, 2023). "To exclude the possibility that the IL-4 post-stimulation-dependent reductions in S.tm CFU were dependent on the ratio of bacteria to macrophages, we investigated these observations at a multiplicity of infection (MOI) to 0.1, 1 and 5 and analysed S.tm CFU after 0.5 h, 4 h and 24 h of infection." (PMID 37190073, 2023). "Notably, IL-4 levels were either very low or undetectable after mRNA-LNP vaccination, indicating a vaccine profile that avoids the establishment of TH2-bias and the possible exacerbation of infection or counteracting TH1 responses." (PMID 36871059, 2023). "However, the immune response in the liver at late stages of the primary infection exerted a mixed Th1/Th2 response including the participation of cytokines such as IL-1β, TNF-α, TGF-β and IL-4 as it has been reported during acute and chronic stages in ruminants and other species." (PMID 36627694, 2023). "Furthermore, we observed that villi pre-treated with rP21 with subsequent infection with T. gondii did not alter IL-4 and IL-6 production in relation to villi infected or not with T. gondii." (PMID 37915581, 2023).
infection (continued). "However, several critical cytokines (IL-4 and IL-10) of the Th2 response have opposite killing effects on protoscoleces by elevating the levels of NO, which enhances the cytotoxic effect in C57BL/6 mice upon infection." (PMID 37637465, 2023). "Having observed that MtbEspR positively regulates the IL-4 promoter and knowing that IL-4 is critical for the shift towards Th2-type immune response, we next investigated the cytokines that are released from THP-1 upon infection with M.smeg::MtbEspR and compared that with M.smeg::pMSP12 infection." (PMID 37928551, 2023). "Pro-inflammatory (IFNγ, IL-6, TNFα), Treg (IL-10, TGFβ1, TGFβ3), Th9 (IL-9), Th17 (IL-17), and Th2 (IL-4, IL-13) cytokines, total IgM and IgG, as well as gene expressions of FoxP3, STAT5+, IFNγ-R1, and ROR alpha+, were measured at day 1, day 7, day 14, day 21, and day 28 post-infection." (PMID 37569646, 2023). "High infection intensity of S. mansoni should be probably controlled by a major locus SM1 mapped to chromosome 5q31-q33 that contains three cytokine genes notably Interleukin 4 (IL4), Interleukin 13 (IL13) and Interleukin 5 (IL5) that are implicated in the Th2 immune response." (PMID 36889485, 2023). "Therefore, IL-4 and IL-10 may play an important role in PTB, characterized by infection and inflammation." (PMID 35860261, 2022). "Unlike in control mice there was no significant increase in IL-4 or IL-13 serum levels in CD1d-/- mice detectable at day 5 pi suggesting that iNKT cells are major producers of these cytokines during early infection." (PMID 36159876, 2022). "While IFNγ, IL-4, IL-10, and IP-10 did not seem to directly correlate with antibody response amongst our cohorts, they were elevated in moderate and severe COVID-19 disease, compared to mild infection." (PMID 36865568, 2022). "The higher concentrations of IL-8, IP-10 and TNFα (proinflammatory response) when compared to IL-4 or IL-10 (anti-inflammatory response) suggested a induction of proinflammatory response due to the infection in these TB-infected animals, regardless of the study group." (PMID 36439353, 2022). "The level of expression of the six cytokines evaluated in maternal peripheral blood has a behavior similar to that described for placental tissue: five of the six evaluated cytokines show a significant difference between the groups without infection and with infection, except for IL4." (PMID 35077516, 2022). "Together, the use of IL-4 reporter mice (BALB/c and C57BL/6 4get mice) revealed an increase in eosinophils (i.e., SiglecF+CD45+SSC-Ahigh cells), which reached up to 3.5 × 104 cells per ear in C57BL/6 and 6 × 103 cells per ear in BALB/c mice at d6 after infection." (PMID 35894051, 2022). "In addition, the levels of type II cytokines such as IL-4, IL-13, and IL-10 in infected wild-type mice were significantly higher than in the control mice without infection (P < 0.05)." (PMID 36271450, 2022). "In addition, we also found that the mRNA transcript levels of pro-inflammatory cytokines IL-1β, TNF-α, IL-6, and IL-12, and anti-inflammatory cytokines IL-4, and IL-10 tended to decrease (p < 0.05 or p < 0.01) in the cats from the feIFN-ω’ treatment group, compared with the FPV infection group." (PMID 35068319, 2022). "The decrease in transit time was also observed in bolus-infected animals at D7, where levels of IL-4 were also low, indicating that the effect may be time dependent rather than due to the mode of infection." (PMID 36569914, 2022). "Groups of C57BL/6 mice treated throughout infection with neutralizing antibodies for either IL-4 or IL-13, but not mice treated with an IgG control, showed elevated ALT levels at day 7pi suggesting a direct role of these cytokines in limiting liver injury during early acute infection." (PMID 36159876, 2022).